TUBA1A (tubulin alpha 1a)
Diseases named in the same sentence as TUBA1A in open-access papers (continued):
Sharing a sentence is not in itself a finding about the gene and the disease.
cardiovascular disease (1 paper, 2021). "We found that APOA4 and TUBA1A had the same expression pattern in the three experiments and may serve as novel potential biomarkers for complications of OSA, such as cardiovascular disease, cognitive dysfunction, and male hypogonadism." (PMID 34185819, 2021).
TUBA1A also shares sentences with these, for which no sentence is quoted: infection (4 papers); Acute myeloid leukaemia (2); epileptic seizures (2); gastric cancer (2); Hydrocephalus (2); microphthalmia (2); Miller-Dieker syndrome (2); Angelman syndrome (1); asthma (1); autism (1); autism spectrum disorder (1); Brain atrophy (1); cataract (1); cerebellar agenesis (1); Cerebellar atrophy (1); Cerebellar dysplasia (1); Cerebral ischemia (1); cobblestone lissencephaly (1); cognitive disorder (1); congenital cataracts (1); congenital microcephaly (1); cortical dysplasia (1); depression (1); early-onset epilepsy (1); echovirus infection (1); endothelial dysfunction (1); Hepatic steatosis (1); hepatocellular carcinoma (1); hydranencephaly (1); ischemia (1).
A further 15 diseases each share a sentence with TUBA1A in 1 paper.